PIP4K2A (phosphatidylinositol-5-phosphate 4-kinase type 2 alpha)
Description:
Catalyzes the phosphorylation of phosphatidylinositol 5-phosphate (PtdIns5P) on the fourth hydroxyl of the myo-inositol ring, to form phosphatidylinositol 4,5-bisphosphate (PtdIns(4,5)P2). Has both ATP- and GTP-dependent kinase activities. May exert its function by regulating the levels of PtdIns5P, which functions in the cytosol by increasing AKT activity and in the nucleus signals through ING2. May regulate the pool of cytosolic PtdIns5P in response to the activation of tyrosine phosphorylation (By similarity). Required for lysosome-peroxisome membrane contacts and intracellular cholesterol transport through modulating peroxisomal PtdIns(4,5)P2 level. In collaboration with PIP4K2B, has a role in mediating autophagy in times of nutrient stress (By similarity). Required for autophagosome-lysosome fusion and the regulation of cellular lipid metabolism. May be involved in thrombopoiesis, and the terminal maturation of megakaryocytes and regulation of their size (By similarity). Negatively regulates insulin signaling through a catalytic-independent mechanism. PIP4Ks interact with PIP5Ks and suppress PIP5K-mediated PtdIns(4,5)P2 synthesis and insulin-dependent conversion to PtdIns(3,4,5)P3.
Synonyms: PI5P4KA; PIP5K2A; PIP5KIIA; PIP5KIIalpha; PIP5KII-alpha; PIPK
Tractability: Small molecule: a structure with a bound ligand is known; a high-quality ligand is known. Antibody: its Gene Ontology location is reachable by antibodies, with high confidence; UniProt places it where antibodies can reach, with medium confidence; the Human Protein Atlas places it where antibodies can reach. PROTAC: ubiquitination databases record sites on it; its protein half-life has been measured; a small molecule that binds it is known.
Target class: Enzyme; Transferase
Chemical probes: ARUK2002821 (high quality), BAY-091 (high quality), THZ-P1-2 (high quality), TM-04-176-01 (high quality)
Gene: Protein-coding gene on chromosome 10 (22,534,854 to 22,714,578, reverse strand). Ensembl gene ENSG00000150867.
Subcellular location: Cell membrane; Nucleus; Lysosome; Cytoplasm; Photoreceptor inner segment; Cell projection, cilium, photoreceptor outer segment
Subcellular location (Human Protein Atlas): Golgi apparatus; Cytosol; Plasma membrane
Pathways (Reactome):
Metabolism: Synthesis of PIPs at the plasma membrane; Synthesis of PIPs in the nucleus
Signal Transduction: PI5P, PP2A and IER3 Regulate PI3K/AKT Signaling
Gene Ontology:
Molecular function: 1-phosphatidylinositol-4-phosphate 5-kinase activity; 1-phosphatidylinositol-5-phosphate 4-kinase activity; protein binding; protein homodimerization activity; phosphatidylinositol kinase activity
Biological process: 1-phosphatidyl-1D-myo-inositol 4,5-bisphosphate biosynthetic process; negative regulation of insulin receptor signaling pathway; positive regulation of autophagosome assembly; regulation of autophagy; vesicle-mediated cholesterol transport; autophagosome-lysosome fusion; phosphatidylinositol phosphate biosynthetic process; megakaryocyte development; phosphatidylinositol metabolic process
Cellular component: autophagosome; cytoplasm; cytosol; nucleus; plasma membrane; lysosome; nucleoplasm; photoreceptor inner segment; cell body; neuron projection terminus; photoreceptor outer segment
Genetic constraint (gnomAD): Loss-of-function variants: 8 observed, 23.18 expected, observed/expected ratio (o/e) 0.35, 90% interval 0.2 to 0.62. The upper end of that interval is the gene's LOEUF score, 0.62, which puts it in group 2 of 6, group 1 being the genes least tolerant of losing a copy. Missense variants: 314 observed, 379.12 expected, observed/expected ratio (o/e) 0.83, 90% interval 0.75 to 0.91. Synonymous variants: 146 observed, 145.93 expected, observed/expected ratio (o/e) 1, 90% interval 0.87 to 1.15.
Homologues: Orthologues: chimpanzee PIP4K2A (100% identical), dog PIP4K2A (100% identical), macaque PIP4K2A (100% identical), pig PIP4K2A (99% identical), mouse Pip4k2a (98% identical), rat AABR07028769.1 (98% identical), guinea pig PIP4K2A (97% identical), rabbit PIP4K2A (95% identical), tropical clawed frog pip4k2a (92% identical), zebrafish pip4k2aa (87% identical), zebrafish pip4k2ab (83% identical), Drosophila melanogaster PIP4K (57% identical), and 1 more. Paralogues in human: PIP4K2B (78% identical), PIP4K2C (64% identical), PIP5K1A (31% identical), PIP5K1C (30% identical), PIP5K1B (29% identical), PIP5KL1 (22% identical).
Diseases named in the same sentence as PIP4K2A in open-access papers:
PIP4K2A is named in the same sentence as 30 diseases in open-access papers, as found by Europe PMC text mining. Sharing a sentence is not in itself a finding about the gene and the disease. The quoted sentences say what the papers report.
schizophrenia (10 papers, 2010 to 2023). A major psychotic disorder characterized by abnormalities in the perception or expression of reality. "A potential gene candidate involved in dopaminergic neurotransmission might be the PIP4K2A (phosphatidylinositol-5-phosphate-4-kinase type 2 α), which has been associated with the risk of schizophrenia, as well as tardive dyskinesia." (PMID 34681036, 2021). "Interestingly, PIP4K2A rs2230469*CC genotype was previously found to be a relative risk factor for schizophrenia." (PMID 34681036, 2021). "In other studies, associations have been proposed between PIK4CA and PIP4K2A (previously named PIP5K2A) and schizophrenia." (PMID 31507376, 2019). "In the present study we investigated the possible association of polymorphisms from five candidate genes RGS4, SLC6A3, PIP4K2A, BDNF, PI4KA with response to antipsychotic in variably ill schizophrenia patients." (PMID 25025909, 2014). "Single locus analysis showed significant association of nine variants from SLC6A3, PIP4K2A and BDNF genes with incomplete antipsychotic response in schizophrenia patients with high severity." (PMID 25025909, 2014). "With this background, in the present study, we investigated 53 polymorphisms from five genes (RGS4, SLC6A3, PIP4K2A, BDNF and PI4KA) in 423 south Indian schizophrenia cases segregated into low and high severity of illness to assess their influence on antipsychotic response." (PMID 25025909, 2014). "PIP4K2A was reported to play a role in biological pathways that may be impaired in schizophrenia." (PMID 38063329, 2023). "PIP4K2A and PI4KA have been suggested as putative susceptibility genes on both positional and functional grounds as these are part of phosphoinositide signaling pathway which is implicated in schizophrenia etiology and may modulate antipsychotic response." (PMID 25025909, 2014).
acute lymphoblastic leukemia (4 papers, 2018 to 2025). Leukemia with an acute onset, characterized by the presence of lymphoblasts in the bone marrow and the peripheral blood. "PIP4K2A encodes the Phosphatidylinositol-5-Phosphate 4-Kinase Type 2 Alpha protein, associated with acute lymphoblastic leukemia susceptibility in humans." (PMID 39943110, 2025). "Genome-wide association studies have revealed that germline genetic variations, including variations in ARID5B, GATA3, PIP4K2A, and ERG, are common in Hispanic populations, and this partly explains the excess of acute lymphocytic leukemia (ALL) cases among Hispanic children and adolescents." (PMID 33287098, 2020).
breast carcinoma (4 papers, 2019 to 2023). "Additionally, HER2+ breast cancer samples generally overexpress both PIP4K2B and PIP4K2A." (PMID 32230859, 2020).
leukemia (3 papers, 2018 to 2022). A malignant (clonal) hematologic disorder, involving hematopoietic stem cells and characterized by the presence of primitive or atypical myeloid or lymphoid cells in the bone marrow and the blood. "In a targeted knockdown screen for phosphoinositide modulator-related genes, PIP4K2A was identified as essential for the survival, proliferation, and clonogenicity of leukemia-initiating cells in humans and murine models." (PMID 36347832, 2022). "In hematological malignancies, PIP4K2A has been identified as an essential protein for the proliferation, clonogenicity, and survival of leukemia-initiating cells." (PMID 36347832, 2022). "PIP4K2A is noticed to be frequently overexpressed in multiple other types of leukemia and solid cancers from cancer cohorts including TCGA, and associated with its candidates in subtype-specific and cancer-specific manners." (PMID 30697230, 2018). "Our findings reveal the transcriptional regulatory network of PIP4K2A in leukemia, and suggest its potentially important role on molecular subtypes of multiple cancers and subsequent treatment outcomes." (PMID 30697230, 2018). "In this study, we conducted array based genome-wide gene expression association analyses to investigate the potential regulatory network of PIP4K2A in leukemia, which is proved to be efficient in our previous work." (PMID 30697230, 2018). "Indeed, PIP4K2A depletion attenuated the growth of primary leukemia blasts but did not significantly affect the clonogenic or multilineage differentiation potential of healthy hematopoietic stem cells." (PMID 36347832, 2022).
acute myeloid leukemia (2 papers, 2020 to 2023). Acute myeloid leukemia (AML) is a group of neoplasms arising from precursor cells committed to the myeloid cell-line differentiation. "Furthermore, microarray gene expression analysis showed that PIP4K2A and AEP are both ubiquitously expressed in a wide variety of healthy tissues, but that expression levels of AEP were lower in primary acute myeloid leukemia (AML)." (PMID 32218783, 2020).
Obesity (2 papers, 2023 to 2024). Accumulation of substantial excess body fat. "Based on this study, an interesting hypothesis is that PIP4K2a mediated the phosphorylation of PtdIns5P to generate various phosphoinositide species may contribute to ciliopathies associated obesity, and MIF may be involved in this process." (PMID 38052787, 2023). "Decreased abundance of PIP4K2A in these cells suggests that PIP4K2A could be responsible at least in part for the platelet alterations observed in obesity." (PMID 38703299, 2024).
sarcoma (2 papers, 2023). A usually aggressive malignant neoplasm of the soft tissue or bone. "Elevation of one of these peroxisomal/mitochondrial interaction regulators (phosphatidylinositol-5-phosphate 4-kinase type 2 alpha; PI5P4Kalpha) is also correlated with advanced, aggressive status in sarcomas (op cit)." (PMID 37762668, 2023).
bipolar disorder (1 paper, 2020). A disorder of the brain that causes unusual shifts in mood, energy, activity levels and the ability to carry out day-to-day tasks. "Genetic studies of PIP4K2A showed an association with bipolar disorder and schizophrenia, as well as with response to pharmacological antidepressant treatment." (PMID 33193575, 2020). "In addition, the mechanisms underlying lithium’s therapeutic efficacy in the chronic treatment of bipolar disorder include differential expression of PIP4K2A." (PMID 33193575, 2020).
breast tumor (1 paper, 2018).
ciliopathies (1 paper, 2023). "This study shows that PIP4K2a as a kinase functions in opposite to INPP5E to contribute to ciliopathies, which may directly link phosphoinositide signaling to primary cilium stability." (PMID 38052787, 2023). "In addition, PIP4K2a may also regulate ciliopathies through its interaction and phosphorylation of MIF to increase 14-3-3ζ mediated MIF nuclear translocation." (PMID 38052787, 2023).
ovarian carcinoma (1 paper, 2025). A malignant neoplasm originating from the surface ovarian epithelium. "An interesting observation is that two proteins, PI3K delta isoform (PIK3CD) and phosphatidylinositol-5-phosphate 4-kinase type-2 alpha (PIP4K2A) in this module are also involved in the PI3K signaling pathway, which is critical for cell survival and frequently altered in ovarian cancer." (PMID 40568132, 2025).
prostate adenocarcinoma (1 paper, 2023). "PIP4K2A, PIP4K2B, and PIP4K2C transcript expression was detected in clinically localized [The Cancer Genome Atlas (TCGA)-Prostate Adenocarcinoma (PRAD), N = 498] and advanced, metastatic PCa [Stand Up 2 Cancer-Prostate Cancer Foundation (PCF) (SU2C, N = 209)] datasets." (PMID 36724278, 2023).
prostate tumors (1 paper, 2023).
cancer (10 papers, 2015 to 2024). A tumor composed of atypical neoplastic, often pleomorphic cells that invade other tissues. "Therefore, we further investigated the expression profile of PIP4K2A and its associated genes in other cancer types with paired tumor/normal tissues from The Cancer Genome Atlas (TCGA)." (PMID 30697230, 2018). "Although limited reports suggested the oncogenic role of PIP4K2A in cancers, regulatory network and prognostic effect of this gene remains poorly understood in tumorigenesis and leukemogenesis." (PMID 30697230, 2018). "In particular, lower expression of PIP4K2A in tumors is associated with longer overall survival in all these cancer types except KIRC, suggesting the potential prognostic role of PIP4K2A overexpression in multiple cancer types, which is frequently observed." (PMID 30697230, 2018). "Due to the potentially important role of PIP4K2A in tumors, we further explored the possible role of PIP4K2A expression on survival rate in different cancer types." (PMID 30697230, 2018). "Due to extensive expression and pleiotropic effect of PIP4K2A in multiple tissues, it is important to unravel the transcriptional regulatory network of PIP4K2A in different cancer types, which is yet time/effect-consuming." (PMID 30697230, 2018). "However, we noticed that PIP4K2A overexpression is related to worse treatment outcomes of multiple cancer types of TCGA, except higher PIP4K2A expression related to better survival status in KIRC." (PMID 30697230, 2018). "Since knockdown of PIP4K2A only exerts inhibitory effects on tumor cells, this selective effect implies that PIP4K2A might be a candidate target for cancer treatment." (PMID 30697230, 2018). "Additionally, opposite association directions of tumor vs. normal were also observed, such as MED16 in THCA, indicating the varied regulatory status and role of PIP4K2A on tumor vs. normal tissues in different types of cancers." (PMID 30697230, 2018). "In this study, we conducted genome-wide gene expression association analyses in pediatric B-ALL cohorts to discover expression associated genes and pathways, which is followed by the bioinformatics analyses to investigate the prognostic role of PIP4K2A and its related genes in multiple cancer types." (PMID 30697230, 2018).
tumor (7 papers, 2018 to 2024). "PIP4K2A is largely implicated in basal cellular activities such as proliferation, survival, glucose uptake and migration, and plays an essential role for tumor growth." (PMID 30697230, 2018). "Both PIP4K2A and eIF4EBP1 have been shown to be involved in tumor progression, suggesting a common link between the two." (PMID 34124142, 2021). "PIP4K2A has been shown to be predominantly cytosolic and regulate cell proliferation and tumor progression." (PMID 34124142, 2021). "In the present study, we have identified PIP4K2A as a putative tumor suppressor and demonstrated its inhibitory effects in PI3K’s signaling pathway and clonogenic growth via modulating p85/p110 PI3K complex stability in PTEN-deficient GBMs." (PMID 30898893, 2019). "A full detailed function of PIP4K2A protein under cellular mechanism still remains elusive, and recent findings suggest that its family is actively involved in oxidative stress, cellular senescence, and tumor growth." (PMID 30898893, 2019). "To examine whether the tumor-suppressive role of PIP4K2A is dependent on its kinase activity, we generated and integrated inactive mutants PIP4K2AN251S and PIP4K2AG131L/Y138F into GBM cells and assessed their inhibition effects on AKT phosphorylation and short-term proliferative kinetics." (PMID 30898893, 2019). "Moreover, loss or even opposite direction of correlations were observed in quite a few genes between tumor and normal tissues, suggesting tumor-specific dysfunction of PIP4K2A regulatory network may contribute to tumorigenesis." (PMID 30697230, 2018).
psychiatric disorder (1 paper, 2020). A disorder characterized by behavioral and/or psychological abnormalities, often accompanied by physical symptoms. "GSK3B, BDNF, NGF, NRG1, HTR2C, and PIP4K2A play important roles in molecular mechanisms of psychiatric disorders." (PMID 33193575, 2020). "GSK3B, BDNF, NGF, NRG1, HTR2C, and PIP4K2A are genes that showed some importance in the study of the molecular etiology of psychiatric disorders." (PMID 33193575, 2020).
PIP4K2A also shares sentences with these, for which no sentence is quoted: Depression (2 papers); acromelic dysplasia (1); Anxiety (1); bacterial infection (1); diffuse large B-cell lymphoma (1); glioblastoma (1); glioma (1); lung adenocarcinoma (1); lung carcinoma (1); manic episodes (1); neurodegenerative disease (1); proliferative vitreoretinopathy (1); prostate carcinoma (1); type 2 diabetes mellitus (1).